TIGAR (TP53 induced glycolysis regulatory phosphatase)
Diseases named in the same sentence as TIGAR in open-access papers (continued):
Sharing a sentence is not in itself a finding about the gene and the disease.
cancer (83 papers, 2011 to 2026). A tumor composed of atypical neoplastic, often pleomorphic cells that invade other tissues. "This review highlights the role of TIGAR in different types of cancer, evaluating its potential role as a diagnostic marker and a therapeutic target." (PMID 40277923, 2025). "Loss of TIGAR promotes the production of cytokines by cancer cells that induce changes in the surrounding fibroblasts to adopt a tumor-supportive phenotype." (PMID 39636862, 2024). "We also show that modulation of TIGAR expression and ROS levels promotes cytokine production by the cancer cells, driving the acquisition of cancer-supporting phenotypes in tumor-associated fibroblasts and myeloid cells." (PMID 39636862, 2024). "PGK1 plays an important role in the progression of cancer through its involvement in the regulation of cancer cell proliferation and tumorigenesis, while TIGAR inhibits glycolysis and protect cells from ROS-associated apoptosis." (PMID 36919762, 2023). "This shift to the PPP metabolism has been commonly seen in cancer cells but it was primary linked to the activation of different antioxidant response systems disentangled from HO-1, TIGAR activation is an example." (PMID 33923744, 2021). "One of the underlying mechanisms is that TIGAR overexpression inhibits glycolysis to produce more antioxidants for cancer cell survival and, on the other hand, reprograms ESCC cell metabolism using glutamine to produces more energy for cancer progression." (PMID 32206103, 2020). "The deregulated TIGAR expression has been associated with tumorigenesis and poor disease prognosis in several cancers." (PMID 31892967, 2020). "In terms of function, TIGAR not only protects cancer cells from oxidative stress-caused damages, but also inhibits the glycolysis process." (PMID 31799200, 2019). "We found that CNAs in core glycolysis enzymes (e.g., HK2) and other cancer‐linked metabolic enzymes such as TIGAR are coordinately enriched in tumors with distinct CNA signatures." (PMID 28202506, 2017). "TIGAR overexpression is also linked to increased glycolytic rate and decreased cell death, important (emergent) cancer hallmarks." (PMID 26238291, 2016). "We previously demonstrated that increased ROS following loss of TIGAR promotes various cancer cell–intrinsic changes that contribute to metastatic capacity, including epithelial to mesenchymal transition, enhanced migration and invasion, and an increase in ERK signaling." (PMID 39636862, 2024). "Overexpression of TIGAR has been associated with some types of human cancer." (PMID 32206103, 2020). "TIGAR protected cancer cells from oxidative stress-caused damages, but also glycolysis defects." (PMID 31799200, 2019).
cancer (continued). "Interestingly, like HMOX-1, TIGAR is implicated in cancer cell-survival and proliferation." (PMID 31251786, 2019). "Besides, TIGAR deficiency has been reported to reduce tumor growth and improve survival in a mouse intestinal adenoma model, while elevated TIGAR expression supported cancer progression." (PMID 30234009, 2018). "Since the overexpression of TIGAR inhibits glycolysis, cancer cells tend to use a compensatory energy-providing pathway to increase ATP production and sustain the survival and progression of ESCC via activating AMPK." (PMID 40277923, 2025). "TIGAR has been found to play an important role in the development of invasive primary cancers by inhibiting oxidative stress." (PMID 40277923, 2025). "Then, we will focus on its involvement in the metabolic reprogramming and spread of cancer cells, delving into the presence and impact of TIGAR in different types of cancers and emphasizing pancreatic and colorectal cancer." (PMID 40277923, 2025). "The role of TIGAR has been emerging as a prognostic and potential therapeutic target in different types of cancers." (PMID 40277923, 2025). "TIGAR increases in the initial stages of cancer, consistent with its role in hindering ROS and encouraging the survival of the preinvasive cells." (PMID 40277923, 2025). "By inhibiting glycolysis, TIGAR can reduce the proliferation rate of cancer cells, particularly in early-stage tumors or specific tissue types." (PMID 40277923, 2025). "Secondly, TIGAR’s expression varies across different cancer types and stages, affecting its reliability and consistency as a universal biomarker." (PMID 40277923, 2025). "TIGAR modulation has been suggested as an effective tool in the therapeutic strategy for a myriad of cancers." (PMID 40277923, 2025). "TIGAR helps protect cancer cells from excessive ROS by promoting the pentose phosphate pathway (PPP), which generates NADPH—a key molecule involved in antioxidant defense." (PMID 40277923, 2025). "Understanding TIGAR expression in different cancer types and its relationship with patients’ survival rate can be an attractive tool for cancer therapeutics and useful for clinical diagnosis and prognosis." (PMID 40277923, 2025). "There is also evidence that TIGAR influences metabolic processes in cancer cells, including the regulation of oxidative phosphorylation (OXPHOS) markers." (PMID 40277923, 2025). "Our study shows that in addition to affecting the behavior of the cancer cell, TIGAR and ROS can impact surrounding cells to modulate tumor aggression." (PMID 39636862, 2024). "TIGAR is a fructose-2,6-bisphosphatase that plays an important role in regulating metabolism, ROS, and cancer development." (PMID 39682267, 2024). "We find that ROS levels in the cancer cells impact their interaction with surrounding normal stromal cells, with higher ROS in cancers that have lost TIGAR inducing a more tumor-supportive behavior of surrounding fibroblasts and macrophages." (PMID 39636862, 2024). "To explore the effect of TIGAR modulation on the interaction of cancer cells with the stromal cells of the TME, we examined PDAC tumors from both KFC-KO and KPC-Tg mice." (PMID 39636862, 2024). "Recent studies suggest that various cancer tissues, including those in GC, exhibit increased levels of TIGAR and that certain types of cancer are suppressed after knockdown of TIGAR." (PMID 35840932, 2022).
cancer (continued). "Our experimental results suggest that TIGAR is highly expressed in GPL in both rat gastric mucosal tissues and human gastric mucosal tissues, which is consistent with the results for TIGAR expression in several types of cancer." (PMID 35840932, 2022). "In cancer models, TIGAR plays a complex role in the formation and progression of different types of cancer via suppressing aerobic glycolysis and controlling reactive oxygen species (ROS) production." (PMID 35254259, 2022). "Of note, TIGAR plays a dual role in cancer cell survival through regulating apoptosis and autophagy, as reported by Xie." (PMID 35165280, 2022). "Recently, it has been reported that TIGAR can both enhance the development of premalignances and suppress the metastasis of cancer invasion by the way of inhibition of ROS production." (PMID 35254259, 2022). "In this study we investigated the role of NRF2 in the regulation of TIGAR in human carcinoma cell lines." (PMID 35163828, 2022). "Accordingly, downregulation of NRF2 decreased the expression of TIGAR in carcinoma cell lines from different origin." (PMID 35163828, 2022). "Exposure of carcinoma cells to electrophilic molecules or overexpression of NRF2 significantly increased expression of TIGAR, in parallel to the known NRF2 target genes NQO1 and G6PD." (PMID 35163828, 2022). "Although TIGAR inhibits the glycolytic pathway, increased protein expression has been reported in cancer cells, indicating that it activates survival mechanisms through other mechanisms." (PMID 34681206, 2021). "In particular, TIGAR has the ability to limit the autophagy activity of cancer cells by regulating the production of ROS." (PMID 33532040, 2021). "Our results indicate that in lymphocytes TIGAR can prevent autophagy, as it was previously shown in cancer cells." (PMID 34299056, 2021). "Then, as the tumor progresses, decreasing levels of TIGAR appear to increase the malignancy of cancer cells consistent with the selection for invasive cells with a higher ROS scavenging capacity." (PMID 34829708, 2021). "We and others have demonstrated that TIGAR is highly expressed in many different human cancers and frequently correlates with an aggressive disease phenotype, therapy-resistance, and poor clinical outcomes." (PMID 35291688, 2021). "Analogously to what occurs in cancer cells, the expression of TIGAR and PFKFB3 allows for a high glycolytic flux together with increased capacity for DNA synthesis and control ROS levels in activated lymphocytes." (PMID 34299056, 2021). "Other studies have also pointed out the possibility of using TIGAR as a therapeutic target for cancer treatment." (PMID 34299056, 2021).
cancer (continued). "Despite the role of TIGAR in cancer cell metabolism being widely explored since 2006, very little is known about the regulation of this enzyme in healthy tissues under physiological conditions." (PMID 34299056, 2021). "g., glutamine and pentose phosphate) that cancer cells shift to since TIGAR overexpression produces more antioxidants against apoptosis and more intermediates for DNA synthesis 17,30." (PMID 32206103, 2020). "Using a pancreatic tumor model, we show that deletion of Tigar drives increased ROS and a decrease in the development of premalignant PanIN lesions, consistent with an enhanced proliferative capacity of cancer cells with higher TIGAR expression." (PMID 31983610, 2020). "We then established ESCC cell lines (KYSE150 and KYSE30) with TIGAR knockout or stable overexpression to verify this gene effects on cancer cell growth in vitro and in vivo in mice." (PMID 32206103, 2020). "Since glycolysis is the major and necessary energy metabolism maintaining the proliferation of cancer cells, the inhibition of glycolysis by TIGAR overexpression in ESCC cells hints the existence of a compensatory energy-providing pathway." (PMID 32206103, 2020). "Collectively, these results suggest an important role of TIGAR in cancer development and in modifying the response to PARP inhibitors." (PMID 31508509, 2019). "While the first two aspects provide mechanisms of how TIGAR downregulation sensitizes cancer cells to olaparib, the latter reveals a possibility of targeting TIGAR as a promising strategy to prevent cancer progression." (PMID 31508509, 2019). "In cancer cells, TIGAR plays an important role in regulating glycolytic flux and promotes NADPH and antioxidant regeneration through oxidative PPP52, and TIGAR KD results in a decrease in NADPH, an increase in ROS, and higher basal levels of DNA damage." (PMID 31508509, 2019). "Along with our present study, several studies have shown the potential of targeting TIGAR to enhance therapeutic effects of cancer therapies." (PMID 31508509, 2019). "TIGAR not only protected cancer cells from oxidative stress condition, but also inhibited the glycolysis process." (PMID 31799200, 2019). "GSEA from RNA sequencing indicates TIGAR KD produces a gene signature that is similar to BRCA1 downregulated cancer cells." (PMID 31508509, 2019). "Under nutrient starvation or metabolic stress conditions, TIGAR acts as a negative regulator of autophagy and plays anti-apoptotic roles in cancer cells." (PMID 31456661, 2019). "Collectively, these results indicate that TIGAR modifies cellular response to PARP inhibitors in cancer cells and presents a novel therapeutic target for developing cancer therapies." (PMID 31508509, 2019). "To assess the effect of TIGAR KD on cancer cell metabolism, we performed targeted metabolomic profiling of TIGAR KD cells stably expressing inducible shRNA against TIGAR." (PMID 31508509, 2019). "TIGAR functions as an inhibitor of glycolysis pathway which seems to be harmful for cancer cell survival." (PMID 31799200, 2019). "Considering the established evidence that cancer cells need to maintain a suitable level of ROS to facilitate tumorigenesis, TIGAR plays an important role in intracellular ROS regulation through NADPH production." (PMID 31799200, 2019). "Our data indicated that TIGAR knockdown was capable of significantly modifying cancer cell proliferation." (PMID 31799200, 2019). "To confirm this possibility, we performed EdU labeling of cancer cells following transient KD of TIGAR by siRNAs." (PMID 31508509, 2019). "In cancer cells, TIGAR suppressed reactive oxygen species (ROS) levels and inhibited autophagy in response to metabolic stress." (PMID 31456661, 2019).
cancer (continued). "Similar results were obtained with SRB assay in two additional cancer cell lines, which are less sensitive to olaparib, suggesting that downregulation of TIGAR sensitizes these cells to olaparib." (PMID 31508509, 2019). "In GC cells under oxidative stress, TIGAR knockdown significantly increased cell apoptosis compared with control cells, indicating that TIGAR played a protective role in cancer cell survival." (PMID 31799200, 2019). "Given its pivotal role in antioxidant regeneration, it is not surprising that our genome-scale CRISPR/Cas9 screen identifies C12orf5 (TIGAR) as a dropout candidate gene involved in sensitizing cancer cells to PARP inhibitor olaparib." (PMID 31508509, 2019). "Our results indicate TIGAR should be explored as a therapeutic target for treating cancer and extending the use of PARP inhibitors." (PMID 31508509, 2019). "To check if an increase in senescence results in reduced clonogenicity, we used three different shRNAs to stably KD TIGAR expression in two different cancer cell lines, OVCA420* and OV90." (PMID 31508509, 2019). "Recent evidence showed that overexpression of TIGAR in carcinoma cells altered metabolic compartmentalization to a mitochondrial metabolic phenotype and ultimately increased tumor growth." (PMID 30814486, 2019). "Evidence has shown that overexpression of TIGAR in carcinoma cells increases the expression of PGC-1α, NRF1, MitoNEET, and Tomm20, which are important markers of mitochondrial biogenesis and OXPHOS32." (PMID 30814486, 2019). "A variety of signaling pathways including NF-κB and Met are involved in the role of TIGAR in cancer." (PMID 29753331, 2018). "PFKFB and TIGAR enzymes control this cycle and are overexpressed in cancer cells, acting as prognostic markers." (PMID 30234009, 2018). "Here, our in vitro and in vivo data strongly indicate that TIGAR is indispensable for cancer cell invasion and metastasis." (PMID 29753331, 2018). "TIGAR mRNA is expressed in all the tissues in which it has been analyzed to date and is overexpressed in several cancer cells." (PMID 30234009, 2018). "It is worth noting that intrahepatic and pulmonary metastases showed that TIGAR was significantly expressed in the nucleus of cancer cells." (PMID 29753331, 2018). "TIGAR is dysregulated in many types of cancer and is involved in in various biological processes such as metabolism, apoptosis, autophagy, cell cycle and cell death." (PMID 29753331, 2018). "This novel finding was consistent with the demonstration that specific downregulation of TIGAR by siRNA induced cancer cell death by altering the pentose phosphate pathway, which is the major pathway regulating production of cellular NADPH." (PMID 29467382, 2018). "Other studies by the same group have shown that the metabolic coupling between cancer cells and fibroblasts contribute to tamoxifen resistance, as CAFs enhanced TIGAR activity in cancer cells, that protected against tamoxifen-induced apoptosis." (PMID 30234009, 2018). "Overexpression of TIGAR has also been found to increase proliferation, while catalytically inactive TIGAR suppresses the tumor proliferation in carcinoma cells, thus reemphasizing the importance of metabolic symbiosis in tumor progression." (PMID 28447025, 2017).